VCAN (versican)
Diseases named in the same sentence as VCAN in open-access papers (continued):
Sharing a sentence is not in itself a finding about the gene and the disease.
tumor (continued). "One could argue that signals from the TME could induce parallel production of both versican and CCL2 by tumor cells, which signals could synergize in favor of metastasis colonization." (PMID 33718177, 2021). "Indeed, versican and other ECM proteoglycans have been shown to impact the tumor cell behavior in myriad cancer types, in both human and canine models." (PMID 34631514, 2021). "Versican influences cell migration and proliferation as well as angiogenesis and inflammation processes thus contributing to create a permissive ECM for invasion and metastasis of tumor cells." (PMID 33804223, 2021). "In this regard, DCN is considered as a potent natural inhibitor of tumor cell proliferation and invasion, whereas the other proteoglycans, namely, versican and biglycan, are not." (PMID 34884232, 2021). "The roles of VCAN in cancer are diverse, ranging from activation of the TME to tumor cell effects." (PMID 33430083, 2021). "As high VCAN could lead to poor overall survival prognosis in STAD, we further analyzed it in the GSE84433 and found that VCAN act as a tumor promoter in GC." (PMID 33631054, 2021). "Analysis of bulk tumour mRNA displayed a strong correlation between ACTA2, a marker of MSCs, and matrix remodelling enzymes (MMP2), ECM proteins (VCAN, FN1, COL1A1), immunomodulatory molecules (Serpine1, CXCL12), innate immune cell markers (CD14, ITGAX) and adaptive immune cell markers (CD4)." (PMID 34885111, 2021). "In addition, siRNA experiments showed that VCAN diminished the tumor promoting effects of IRF9 and indicated the involvement of the tumor suppressor CDKN1A." (PMID 33430083, 2021). "Therefore, all those three useful prognostic indicators, LUM, VCAN, and EFNA4 are considered to have a relationship with the immunoregulation of the tumor environment." (PMID 34093807, 2021). "As it is known that PSGL-1 binds versican, and that versican seems to be playing a pro-tumoral role in the TME, it is possible that versican-PSGL-1 interactions in the tumor microenvironment may inhibit T cell infiltration and prevent tumor killing." (PMID 33708224, 2021). "In addition, activation of TLR2 by endogenous extracellular matrix-derived proteoglycan versican and TLR4 by HMGB-1 from damaged cells are known to promote tumor growth in a context-dependent manner." (PMID 32422978, 2020). "Therefore, we infer that the effect of VCAN, CLIP4 and MATN3 expression on the poor survival of GC patients is probably related to the remodeling of stromal components in the tumor microenvironment." (PMID 32754268, 2020). "A lower tumor stage and no expression of versican was correlated sig- nificantly (P<0.001) with longer survival." (PMID 31531098, 2019). "A comparison of hypoxia-treated tumours with and without CDK1i revealed that CDK1i reversed the observed upregulation of expression in the seven up-regulated genes whilst VCAN, whose expression was down-regulated showed a small increase in expression." (PMID 31235824, 2019). "The detection of VCAN proteolysis in the TME may provide a convenient and reliable immune biomarker that can be utilized across tumor types." (PMID 29970158, 2018). "Our data demonstrate that LY can delay tumor growth and ascites formation in OC xenografts and these in vivo effects are correlated with reduced-expression of important stroma-derived proteins COL11A1 and VCAN." (PMID 30087253, 2018). "We show that tumor cell lines, which have not been previously systematically studied in this manner, differ considerably in their versican expression levels." (PMID 29222454, 2017). "Because versican aggregates with HA in various tissues, we combined biotinylated HA-binding protein (HABP) and anti-versican GAGβ staining which revealed their co-localization in the MDA-MB231 tumor stroma." (PMID 29222454, 2017). "Previous studies have mostly focused on the versican expressed by tumor cells or not attempted to distinguish between stromal and cancer cell versican expression." (PMID 29222454, 2017).
tumor (continued). "Furthermore, we found that when non-tumor cells, MCF10A and HBL100, are treated with hATN-CMs, there is actually a decrease in fluorescence intensity for versican." (PMID 28173833, 2017). "For example, VCAN was found to be 29-fold up-regulation in human ACC tumors comparing to normal tissues and increased VCAN protein staining was detected in mouse xenograft tumor models for human ACCs." (PMID 25587024, 2014). "The data presented in this report indicate that a reduction of all forms of versican may abrogate formation of peritoneal lesions seeded by EOC spheroids and it impedes tumor formation by individual cells." (PMID 24999371, 2014). "Interestingly, we discovered that two of the most highly expressed ACC target genes, VCAN and HAPLN1, can bind within a predicted ECM complex in ACC tumor cells and, in the case of HAPLN1, appear to be regulated by RUNX1 activation." (PMID 25587024, 2014). "Of note, versican also binds to TLR-2 and acts as an agonist for the receptor to activate tumor-infiltrating myeloid cells by increasing production of cytokines, like TNF-α, to promote tumor metastasis." (PMID 24213471, 2012). "The coexpression of molecules such as BMP7, VCAN and EpCAM in EOC cells expressing high CD157 further substantiates this view since these molecules are considered negative prognostic markers involved in the control of the progression of various types of tumor." (PMID 22916288, 2012). "The accumulation of versican in non-palpable carcinomas is related to higher tumor grade and the presence of invasive disease in lesions of both MD and MAMCs." (PMID 21791066, 2011). "A recent study has documented that versican can activate tumour-infiltrating myeloid cells through TLR2 and its coreceptors TLR6 and CD14 and elicit the production of proinflammatory cytokines including TNF-α that enhance tumour metastasis." (PMID 20871832, 2010). "Versican, a large multi-domain chondroitin sulfate (CS) proteoglycan, is a major component of the ECM involved in cell adhesion, migration, proliferation and differentiation, all processes vital to tumour development and progression." (PMID 17453002, 2007). "Proteolytic degradation of VCAN by MMPs and ADAMTS produces bioactive fragments, known as matrikines, including versikine, which contributes to the creation of an immunomodulatory environment influencing the migration of CD8+ lymphocytes and promoting immune evasion of the tumor." (PMID 40507957, 2025). "However, an interesting point in our patient is that immunohistochemical staining shows no expression of VCAN in tumor cells." (PMID 39205715, 2024). "Despite these findings in other tumor types, the role of VCAN in DLBCL has not been explored yet." (PMID 38980810, 2024). "In contrast, when VCAN-positive (VCAN+) cells were around the tumor border, we observed less CD8+ T cells present in the tumor parenchyma, thus suggesting VCAN expression on the tumor border may regionally restrict T cells to the stroma preventing access to tumor cells." (PMID 38517140, 2024). "In a recent study, glycan-associated proteins such as CD147, BGN, VCAN, and TNC were found to be enriched in tumor EVs compared to EVs secreting from non-tumor adjacent tissues, which can be potentially used as cancer EV biomarkers or even to identify the cancer origin." (PMID 37773167, 2023). "Finally, the tumor histological classification showed a significant increase in VCAN RNA expression in the non-papillary group compared to the papillary group (p < 0.01)." (PMID 37108649, 2023). "Finally, we performed immunohistofluorescent (IHF) staining on two matched FLC/NML pairs of samples and confirmed that VCAN protein is robustly, though nonuniformly, detected only in tumor tissue." (PMID 36923282, 2022).
tumor (continued). "In fact, we were able to detect five upregulated proteins in the normal mucosa adjacent to the tumor, namely laminin subunit alpha-4 (LAMA4), elastin microfibril interfacer 1 (EMILIN1), LTBP1 and fibrinogen beta chain (FGB), as well as proteoglycan versican core protein (VCAN)." (PMID 35340765, 2022). "Similarly, the level of VCAN expression in tumor tissue was significantly higher than that in surrounding normal tissue from the same sample." (PMID 36203562, 2022). "In monocytes, VCAN expression was higher in adjacent tissue samples than tumor samples (P value-adj = 9.99E − 84); ANGPT2 was not highly expressed in immune cells of tumor samples or adjacent tissue samples; MS4A4A was highly expressed in monocytes of tumor samples (P value-adj = 1.02E − 14)." (PMID 36569220, 2022). "Moreover, they showed that POSTN, FN1, VCAN, and pro-collagen-I (PCOL-I, newly synthesized COL-I) colocalize in extracellular strand and ring structures, visible inside the metastases and at the tumor-stroma interface." (PMID 34858485, 2021). "(Fig- ure-1) Versican was not expressed in 38.1% of tumor samples." (PMID 31531098, 2019). "Versican, a large chondroitin-sulfate proteoglycan, mainly secreted by stromal cells in the ECM, is a recognized cell adhesion and motility modulator that may facilitate tumour cell invasion and metastasis." (PMID 21975223, 2011). "A recent study has documented that versican, a large extracellular matrix proteoglycan, can activate tumour-infiltrating myeloid cells through TLR-2 and its coreceptors TLR-6 and CD14 and elicit the production of proinflammatory cytokines including TNF-alpha that enhance tumor metastasis." (PMID 20652007, 2010). "Future studies should also delve deeper into the influence of fibronectin on tumor progression, namely, by identifying the specific fibronectin isoforms produced in the tumor, as well as other relevant proteins that have not been covered in this work, such as tenascin-C and versican." (PMID 37190331, 2023). "In contrast, versican and biglycan PGs, other matrix-secreted PGs, accumulate in the peritumoural ECM, stimulate inflammatory pathways, and drive tumour invasion and early relapse in node-negative BC." (PMID 41463344, 2025). "In previous studies, it had been reported that the expression of HOIL-1 and SHARPIN was upregulated in tumor tissues and exerted oncogenic functions by stabilizing the expression HOIP and promoting the transactivation of Versican expression; however, it was independent of their M1-Ubi activity." (PMID 41053347, 2025). "Since there are no validated ACC tumor cell lines we selected a short term culture of a human ACC biopsy collected through an IRB approved protocol and treated cells with either control or 2 different lentiviral VCAN shRNAs." (PMID 25587024, 2014).
cancer (214 papers, 2007 to 2026). A tumor composed of atypical neoplastic, often pleomorphic cells that invade other tissues. "Undetectable VCAN was associated with a significant increase in total CD8+ T cells in ER+ cancers (p = 0.028)." (PMID 40361362, 2025). "VCAN, a chondroitin sulfate proteoglycan, plays a pivotal role in tumorigenesis, with increased expression linked to various cancers and poor prognosis." (PMID 38962317, 2024). "ACAN and VCAN were not only associated with extracellular matrix composition but were also expressed higher in cancer patients." (PMID 37108649, 2023). "Stromal VCAN immunostaining can indicate TGFβ-activated stroma, as it was exclusively stained in the cancer stroma, mainly expressed by CAFs in association with phospho-SMAD3 staining." (PMID 37894310, 2023). "Versican has been associated with several classic features of cancer, such as proliferative signaling, avoidance of growth inhibition signals, resistance to cell death, angiogenesis, and tissue invasion and metastasis." (PMID 37833287, 2023). "Versican and IKKβ are mutually addicted and/or overexpressed in human cancers and possess diagnostic and prognostic power." (PMID 36980752, 2023). "Several studies have found that VCAN is also present in the stroma of various types of cancers and is associated with cancer growth and invasion." (PMID 36275632, 2022). "Increased VCAN expression has been observed in a wide range of malignant tumors and has been associated with both cancer relapse and poor patient outcomes in breast, prostate, and many other cancer types." (PMID 35954429, 2022). "The study has shown that VCAN mRNA specifically expressed in cancer-associated fibroblasts was further confirmed to be a prognostic factor in two additional independent datasets in 453 and 89 stages II/III patients." (PMID 35812745, 2022). "The result showed that VCAN was positively associated with the level of CAFs infiltration in the vast majority of human cancers." (PMID 36203562, 2022). "Both these studies and the results presented here support a role for VCAN in cancer-associated fibroblasts." (PMID 35812745, 2022). "In CD133+/CD44+ prostate CSCs, VCAN causes the suppression of cancer cell attachment to fibronectin and thereby increases cell motility." (PMID 36358747, 2022). "We found that VCAN was associated with infiltration of a variety of immunosuppressive cells, such as macrophages, T cell regulatory (Tregs), and cancer associated fibroblasts (CAFs)." (PMID 36203562, 2022). "VCAN is expressed and secreted by cancer-associated fibroblasts under specific stimuli, such as the transforming growth factor-β (TGFβ)." (PMID 35454809, 2022). "We found that patients with low VCAN expression benefited more from adjuvant chemotherapy, adjuvant chemoradiotherapy and immunotherapy, which was associated with cancer associated fibroblasts." (PMID 36203562, 2022). "In cancer, high expression of the VCAN gene is linked with both high malignancy and poor outcomes in patients." (PMID 33430083, 2021). "Previous studies have shown that increased levels of VCAN are associated with poor prognosis of patients in a wide range of malignant tumors." (PMID 33604385, 2021). "Increased expression of VCAN has been reported in several cancers and is associated with adverse outcomes." (PMID 33564303, 2021). "Overexpression of VCAN has been observed in numerous cancers and their respective metastases but has only been associated with the invasion and motility of breast cancer, prostate cancer, PC, and melanoma, and invasion and migration in renal cell carcinoma." (PMID 34591244, 2021). "In cancer, increased levels of versican are associated with immune cell phenotype, disease prognosis and failure to respond to treatment." (PMID 34527586, 2021). "Intriguingly, versican expression is upregulated by macrophages when co-cultured with carcinoma cells, suggesting that the source of versican includes both myeloid cells associated with cancer cells." (PMID 32265939, 2020).
cancer (continued). "By increasing the expression of the proteoglycan, versican is strongly associated with poor prognosis for many different cancers." (PMID 31531098, 2019). "Versican expression has been linked with poor prognosis and relapse-free survival in cancer patients." (PMID 31334111, 2019). "Lumican and versican are proteins relevant to the biology of cancer and their expression was found to be associated with clinical outcome." (PMID 28481899, 2017). "Accumulating evidence indicates that increased versican expression is associated with unfavorable prognosis for many cancers." (PMID 28035060, 2017). "Among the genes that were upregulated in carcinomas, several well known stroma-associated glycoproteins were present, including lumican and versican." (PMID 28481899, 2017). "Expression of the large CS proteoglycan Versican, which is linked to cell adhesion and associated with poor outcomes in many different cancers including PCa, also responds to androgens." (PMID 27428423, 2016). "Investigation into cancer growth and metastasis has implicated versican as having a central role driven by inflammatory stimuli." (PMID 24653726, 2014). "The presence of the proteoglycan versican has been strongly associated with cancer development and progression." (PMID 23082892, 2012). "Some study also found that VCAN is associated with metastasis in a variety of cancers." (PMID 40386063, 2025). "Besides, the high VCAN expression in different malignant tumors has been linked to an unfavorable prognosis for patients." (PMID 39012409, 2024). "We suggest that ADAMTS1-induced dissemination of cancer cells in vivo might be caused by VCAN-mediated invasion promotion and anoikis resistance." (PMID 39333870, 2024). "Elevated levels of VCAN have been associated with a poorer prognosis in cancer." (PMID 37108649, 2023). "Moreover, VCAN is overexpressed in human KRASMUT cancers and can serve as a diagnostic and prognosis biomarker." (PMID 36980752, 2023). "Interestingly, we found that it was in almost human cancers that VCAN expression was positively associated with the enrichment of these signaling pathways, which demonstrated the potential of VCAN as the common target for cancer treatment." (PMID 36203562, 2022). "Additionally, the expression of versican in tumors was associated with cancer grade and adverse outcome." (PMID 34356118, 2021). "Interestingly, an IPA analysis showed that different regulated genes were positively associated with the invasion and migration process in cancer cells: VCAN, SPARC, IL6, MMP14, IL4R, ICAM, TIMP1 and IGF2." (PMID 32848147, 2020). "Importantly, in cancer-associated inflammation, versican can affect the production of cytokines by both lymphoid and myeloid cells." (PMID 31068944, 2019). "The proteoglycan versican is implicated in growth and metastases of several cancers." (PMID 29222454, 2017). "Although the versican G3 domain has been widely implicated in cancer cell proliferation and metastasis, to date most reports about the G1 domain have been related to its roles in maintaining structural integrity or its interaction with other extracellular matrix molecules like hyaluronan." (PMID 28684419, 2017). "The potential for inhibiting VCAN to enhance the effects of drugs such as cisplatin, gemcitabine and epirubicin shows that VCAN could potentially serve as a biomarker to identify patients who are at a higher risk of developing cancer or who may respond better to drug therapies." (PMID 37108649, 2023). "In this study, we identify a 4-protein sEV biomarker panel (thrombospondin-1, nidogen-1, pentraxin-3, and versican) based on proteomic profiles obtained from an isogenic cancer cell line model." (PMID 41881025, 2026). "VCAN-detectable tumors represented a larger proportion of ER+ cancers than ER− cancers (93% vs. 77%; p < 0.001)." (PMID 40361362, 2025). "The cross-talk between cancer cells and CAFs via VCAN plays a key role in the progression of OC under TGF-β stimulation." (PMID 40369674, 2025).